ALYREF (Aly/REF export factor)
Diseases named in the same sentence as ALYREF in open-access papers (continued):
Sharing a sentence is not in itself a finding about the gene and the disease.
tumor (continued). "Immunohistochemical analysis showed a strong nuclear ALYREF protein staining pattern in xenograft tumor samples of control tumors." (PMID 35776213, 2022). "NSUN2, NSUN5, NSUN6, DNMT3A, DNMT3B, ALYREF, and TET3 acted as tumor risk factors, and overexpression of these genes led to a poorer prognosis for ccRCC patients." (PMID 36661693, 2022). "The overexpression of ALYREF was significantly related to both advanced tumor-node-metastasis stages and poor HCC prognosis." (PMID 34367948, 2021). "Immunoblot analysis of snap-frozen tumor tissues showed a decrease in ALYREF, USP3, and MYCN protein expression as a result of doxycycline treatment, compared to vehicle control." (PMID 33767157, 2021). "The level of NSUN3 and NSUN6 was increased in tumor samples, whereas the level of ALYREF, NSUN5, and NSUN7 was decreased in tumor samples." (PMID 33365328, 2020). "Finally, in a cisplatin-resistant subcutaneous tumor mouse model, ALYREF knockdown significantly reduced cisplatin resistance and led to downregulation of ALYREF, LGR4, and β-Catenin protein levels in tumor tissues." (PMID 41345330, 2025). "Silencing ALYREF significantly decreases tumor growth in vivo by reducing HCC cell proliferation." (PMID 40114967, 2025). "A critical next step will involve systematic delineation of circHIPK3’s network-level regulatory architecture in gallbladder carcinogenesis, including in vivo validation of its interaction with ALYREF and functional characterization of ALYREF’s role in tumor progression." (PMID 40466438, 2025). "Compared to nude mice, ALYREF deficiency resulted in a more significant reduction in tumor weight in C57BL/6J mice, which indicated that ALYREF deficiency could promote antitumor immune response." (PMID 38402198, 2024). "ALYREF overexpression was found to promote tumor metastasis of NPC cells in vitro and in vivo." (PMID 39117671, 2024). "In addition, ALYREF was significantly upregulated in PDAC tumor tissues in the GSE15471 and GSE16515 datasets." (PMID 38402198, 2024). "In addition to fewer immune cells, LUSC patients with high ALYREF expression tend to exhibit greater tumor purity, which suggests a propensity for worse outcomes." (PMID 38361753, 2024). "Furthermore, both ALYREF mRNA expression and ALYREF+ cell rate were closely correlated with tumor size in LIHC tissues in our verification cohorts." (PMID 38164181, 2024). "To further unveil whether the tumor-promoting effects of NOP2 were dependent on ALYREF, we performed western blot and transwell assays." (PMID 39013911, 2024). "In brief, these findings suggest that LINC02159 may perform tumor-promoting roles in NSCLC by interacting with ALYREF." (PMID 37537569, 2023). "Among them, DNMT3b, DNMT1, ALYREF, TET2, NSUN2 and NSUN5 mutations imply that m5C may act abnormally in the tumour." (PMID 37408139, 2023). "Within TREX, the ALYREF protein is a central component that is loaded onto mRNAs co-transcriptionally, promoting pre-mRNA processing and export, and we find that it was elevated in Signature I tumor samples." (PMID 37745397, 2023). "Moreover, the silencing of ALYREF also contributes to a decreased tumour formation ability in the orthotopic xenografts." (PMID 37228185, 2023). "After identifying and establishing that ALYREF expression is relevant in human breast carcinogenesis and influences cellular growth and tumor formation in TNBC in vitro and in vivo, we performed RNA-seq whole transcriptome analysis to better understand the involved molecular mechanisms." (PMID 35776213, 2022). "Importantly, high ALYREF mRNA expression strongly correlated with MYCN expression in ganglia tissues throughout tumor progression." (PMID 33767157, 2021). "Furthermore, our presented findings suggest that NSUN2 promotes tumor growth and metastasis by increasing ALYREF/YBX1-mediated YAP expression in NSCLC and effective inhibition of m5C modification might provide a potential treatment strategy for NSCLC." (PMID 41794778, 2026).
tumor (continued). "Collectively, NSUN2 regulates the tumor immune microenvironment and promotes immune escape in various cancers through multiple molecular axes, including PD-L1, YBX1, ALYREF, and the SNHG15/miR-545-3p pathway." (PMID 41256859, 2025). "As an m5C reader, ALYREF stabilizes oncogenic transcripts—such as EGFP—thereby promoting downstream signaling pathways like STAT3, which are known to drive tumor progression." (PMID 41012587, 2025). "The m5C sites in RNA are recognized by two main readers, Aly/REF export factor (ALYREF) 10, 44, 45 and Y-box binding protein 1 (YBX1) 46-48, which determine the regulatory mechanism and function of m5C modification in tumour cells." (PMID 40860147, 2025). "Mechanistically, TUG1 recruited ALYREF to maintain the stabilization of enhancer of zest homolog 2 (EZH2) mRNA and expression of H3K27me3, repressing the transcription of the tumor-suppressor gene CPEB1." (PMID 40330150, 2024). "Our findings demonstrated the potential of ALYREF to predict clinical prognostic risks in BLCA patients and regulate the tumor immune microenvironment." (PMID 38579085, 2024). "All these results demonstrated that high expression of ALYREF and YBX1 is significantly relevant to tumor immunity." (PMID 38238581, 2024). "Silencing of ALYREF in PDAC cells significantly inhibited cell proliferation in vitro and decreased tumor growth in vivo." (PMID 38402198, 2024). "Among these two cohorts, we found that the expression of ALYREF and NSUN2 were significantly upregulated in UCB tumor tissues compared to adjacent normal tissues." (PMID 36806253, 2023). "Our study unveils a novel m5C dependent cross-regulation between nuclear reader ALYREF and m5C writer NSUN2 in activation of hypermethylated m5C oncogenic RNA, which consequently leads to tumor progression." (PMID 36806253, 2023). "Based on this clinical observation, we further demonstrated a significant influence of ALYREF on the cellular growth of TNBC cells and tumor formation in vivo." (PMID 35776213, 2022). "Regulators with amplificated CNV tended to highly expressed in tumor samples (e.g., DNMT1, ALYREF, and NSUN5), and vice versa (e.g., NSUN7 and NSUN6)." (PMID 36389669, 2022). "Based on the human relevance and proliferative effects in cell lines and in vivo tumor formation in TNBC model systems, we aimed to unravel the mechanism behind ALYREF’s contribution to breast carcinogenesis." (PMID 35776213, 2022). "Microarray mRNA expression analysis showed increasing ALYREF and MYC-signature gene expression throughout tumor progression in ganglia isolated from TH-MYCN+/+ mice in comparison to ganglia from wild-type littermates." (PMID 33767157, 2021). "We also found that ALYREF expression was remarkably co-related to eIF4A3 expression, and that eIF4A3 expression was upregulated in HCC tissues compared to adjacent non-tumor tissues." (PMID 34367948, 2021). "In experimental studies, ALYREF knockdown significantly inhibited HCC cell proliferation and tumor growth, suggesting that ALYREF may be a potential prognostic marker and therapeutic target." (PMID 41180455, 2025). "Furthermore, the expression levels of ALYREF and YBX1 were significantly correlated with immune infiltration of the tumor microenvironment and immune-related modulators." (PMID 38238581, 2024). "Based on the significant correlation between ALYREF expression and LIHC tumor characteristics, we hypothesized that ALYREF plays a functional role in LIHC progression." (PMID 38164181, 2024). "To further explore the mechanistic basis of the tumor-enhancing effects of ALYREF in LIHC, we performed RNA transcriptome sequencing (RNA-seq) technology to identify the gene expression profiles of LIHC cells with ALYREF knockdown." (PMID 38164181, 2024). "Additionally, we assessed the tumor microenvironment, immune checkpoint-related genes, immunomodulators, Tumor Immune Dysfunction and Exclusion (TIDE) score and drug resistance of ALYREF and YBX1." (PMID 38238581, 2024).
tumor (continued). "We further found that after knockdown of ALYREF, colony-formation and cell counting kit-8 (CCK8) assays showed that the reduced tumor cell growth could be rescued by the overexpression of WT ALYREF, but not the K171A-mutant ALYREF." (PMID 36806253, 2023). "TCGA data analysis results showed that ALYREF was significantly upregulated in tumor tissues of NSCLC patients compared to non-tumor tissues, showing an AUC of 0.882." (PMID 37537569, 2023). "The effect of ALYREF knockdown on tumor cell invasion and lung metastasis was rescued by overexpression of WT ALYREF rather than the mutant." (PMID 36806253, 2023). "We then analyzed the expression of ALYREF protein in tumor and non-tumor tissues of NSCLC patients and found that ALYREF protein is highly expressed in 93% of tumor tissues that simultaneously harbored elevated levels of LINC02159." (PMID 37537569, 2023). "Similarly, tumor cells may promote oncogenic expression through m5C, as suggested by the upregulation of its readers, YBX1, YBX2, and ALYREF, which enhance mRNA transport, stability, and translation." (PMID 40918643, 2025). "Using the risk model of m5C regulated genes, it was found that the overexpression of YBX1 gene led to poor prognosis of HCC patients; ALYREF and NSUN4 could also be used as carcinogenic indicators of HCC prognosis and were related to immune infiltration in the tumor microenvironment." (PMID 41180455, 2025). "Overexpression of ALYREF and YBX1 was accompanied by the upregulation of immune checkpoint inhibitors (such as CD276 and PDCD1) and downregulation of immune checkpoint stimulants (such as CX3L1, ITGB2, CD40LG and SELP), which promoted evasion of immune surveillance by these tumor cells." (PMID 38238581, 2024). "ALYREF protein expression was highly upregulated in PDAC tumors compared with the corresponding adjacent non-neoplastic tissues in nine paired samples of tumor tissues and adjacent tissues from The First Affiliated Hospital of Zhejiang University according to western blotting." (PMID 38402198, 2024). "The upregulation of ALYREF was more significant in PDAC tumor tissues compared with normal tissues." (PMID 38402198, 2024). "Since the NSUN2/ALYREF/m5C‐PFAS oncogenic cascade is an important trigger of RB, our study provides a novel targeted m5C reprogramming therapeutic strategy, which may potentially be an efficient anti‐tumour therapy approach." (PMID 37228185, 2023). "As the NSUN2/ALYREF/m5C‐PFAS oncogenic cascade is an important RB trigger, our study suggests that a targeted m5C reprogramming therapeutic strategy may be a novel and efficient anti‐tumour therapy approach." (PMID 37228185, 2023). "Since the NSUN2/ALYREF/m5C‐PFAS oncogenic cascade is an important trigger of RB, our study provides a novel therapeutic strategy, namely, a ‘targeted m5C reprogramming strategy’, that may potentially be an efficient anti‐tumour therapy." (PMID 37228185, 2023). "First, the “writer” genes NSUN1-NSUN7, the “eraser” genes TET2 and ALKBH1, and the “reader” genes ALYREF and YBX1 were significantly upregulated or downregulated in tumor tissues, suggesting these genes may be critical in m5C-related occurrence and progression of COAD." (PMID 35281843, 2022). "The expression of ALKBH1 (p = 0.036), ALYREF (p < 0.001), NOP2 (p < 0.001), NSUN2 (p < 0.001), NSUN4 (p < 0.001), NSUN5 (p < 0.001), NSUN6 (p < 0.001), NSUN7 (p = 0.006), and YBX1(p < 0.001) were significantly upregulated in tumor tissues compared with the adjacent mucosa." (PMID 35281843, 2022). "However, ALYREF mRNA expression shows a negative correlation with tumor-infiltrating cells in LUSC." (PMID 38361753, 2024). "We discovered noteworthy changes in the expression of ALYREF and YBX1 among 33 tumor types compared to corresponding normal tissues." (PMID 38238581, 2024).
cancer (42 papers, 2014 to 2026). A tumor composed of atypical neoplastic, often pleomorphic cells that invade other tissues. "The results revealed that ALYREF was significantly increased and closely associated with poor OS in various cancers (Fig. EV8I–L)." (PMID 41326692, 2026). "Expressed in various tissues and highly involved in the transcriptional regulation, ALYREF has the potential to become a novel diagnostic marker and therapeutic target for cancer patients." (PMID 38491127, 2024). "RNA m5C methylation and its regulators (especially ALYREF) are significantly linked to many human diseases, including cancer." (PMID 37537569, 2023). "Based on our transcriptome analysis after ALYREF knock-down, several RNAs including the short isoform of the cancer-associated noncoding RNA NEAT1, were positively correlated (down-regulated) in the three tested TNBC cell lines." (PMID 35776213, 2022). "TRMT61A is positively associated with Reptin as an m1A writer in 35 types of cancer, and ALYREF, as the m5C reader, was positively associated with Reptin in 35 cancer types." (PMID 35754815, 2022). "Studies have implicated ALYREF as a regulator of cancer cell growth, since depletion of ALYREF results in a significant decrease in cell proliferation." (PMID 33767157, 2021). "ALYREF was dysregulated in human cancers and was linked to poor survival 12-15." (PMID 38164181, 2024). "Similarly, ALYREF was positively associated with numerous immune checkpoints in these cancers, except for DLBC, LUSC, and ESCA." (PMID 38361753, 2024). "Furthermore, ALYREF knockdown caused a significant decrease in cancer cell migration." (PMID 33767157, 2021). "Together, these data indicate that increased expression of ALYREF predicts a poor prognosis for cancer patients." (PMID 41326692, 2026). "Studies have suggested that ALYREF can play an essential role in metastasis, cancer progression, and chemoresistance by modulating cell proliferation, migration, and invasion and antiapoptotic effects 45, 107-110." (PMID 40860147, 2025). "In summary, these results provide supportive evidence that ALYREF and YBX1 are linked to the immunosuppressive microenvironment in cancers." (PMID 38238581, 2024). "In this study, we observed that our research suggests that ALYREF has a broad potential role in various cancers, particularly in urinary tumors and LIHC." (PMID 38361753, 2024). "ALYREF exhibited significant differential expression in various human cancers compared to normal samples, with heightened expression in nineteen cancers and reduced expression in two." (PMID 38361753, 2024). "We divided the clinical database into two groups based on the expression levels of ALYREF and YBX1 to explore their association with the prognosis of pan cancers." (PMID 38238581, 2024). "This study aims to elucidate the immuno-oncological effect of ALYREF in human cancer through a comprehensive pan-cancer analysis, thereby deepening our understanding of this gene’s role in cancer." (PMID 38361753, 2024). "Among the 32 types of cancer, 29 showed an increased level of ALYREF in tumors tissues than in normal tissues, including STAD, liver hepatocellular carcinoma (LIHC), and Pan-kidney cohort (KIPAN)." (PMID 38491127, 2024). "Our findings highlighted the essential function of ALYREF in tumorigenesis and revealed the specific contribution of ALYREF to gastric carcinogenesis through pan-cancer analysis and biological experiments." (PMID 38491127, 2024). "Our study found that ALYREF expression was significantly related to aging, confirming the link between epigenomics, aging, and cancer." (PMID 38361753, 2024). "We found that ALYREF was highly expressed in majority of cancer types and that elevated expression level was positively associated with poor prognosis in many cancers." (PMID 38491127, 2024). "Our findings demonstrated that ALYREF and YBX1, as m5C readers, are aberrantly expressed in most cancers and are associated with disease prognosis." (PMID 38238581, 2024).
cancer (continued). "More and more evidence testified that ALYREF plays an important role in diversified diseases, especially cancers." (PMID 38491127, 2024). "In order to explore the role of ALYREF on tumorigenesis, TCGA and GTEx databases were used to investigate the relationship of ALYREF to pan-cancer." (PMID 38491127, 2024). "This study focuses on the immuno-oncological impact of ALYREF in human cancer through a pan-cancer analysis, enhancing understanding of this gene’s role in cancer." (PMID 38361753, 2024). "ALYREF and YBX1 are both implicated in numerous RNA processing events, and their abnormal expression has been linked to reduced survival rates in cancer patients." (PMID 38238581, 2024). "Here we demonstrated the relationship between ALYREF expression level and the different subtypes in two disparate classification systems, including Asian Cancer Research Group (ACRG) classification and Lauren classification." (PMID 38491127, 2024). "Expression level and pattern analysis based on TCGA and GTEx database revealed that the expression level of ALYREF were significantly increased in majority of cancers." (PMID 38491127, 2024). "Several m5C-modified mRNAs have been identified as the targets of ALYREF in cancers, such as LRRC8A, Myc, PKM2, and YAP1, among others." (PMID 37537569, 2023). "With respect to the two m5C-related regulators (NSUN6 and ALYREF) identified in our results, there have been some studies on cancer and related mechanisms." (PMID 35281843, 2022). "IHC data from the HPA online database also demonstrated that the protein levels of NSUN6 and ALYREF were more highly expressed in cancer tissues than in normal tissues." (PMID 35281843, 2022). "We found that ALYREF gene expression was dysregulated in several cancers and was significantly elevated in HCC patient tissue samples and HCC cell lines." (PMID 34367948, 2021). "ALYREF has also been shown to be involved in multiple RNA processing events, and its aberrant expression has been correlated with poor cancer patient survival." (PMID 34367948, 2021). "ALYREF has been recognized to act as an oncogene in multiple human malignant tumors." (PMID 40914946, 2026). "To evaluate its function in ATC drug resistance, we examined correlations between the expression of 12 m5C regulators [NSUN2-7, TRDMT1 (writers); ALKBH1, TET2, ALKBH3 (erasers); YBX1 and ALYREF (readers)] and drug sensitivity in the Cancer Therapeutics Response Portal (CTRP)." (PMID 40083919, 2025). "In conclusion, ALYREF may serve as an oncogenic biomarker in numerous cancers, meriting further research attention." (PMID 38361753, 2024). "Our findings suggest that ALYREF could serve as an oncogenic biomarker in many cancer patients and should be given more attention by researchers." (PMID 38361753, 2024). "Based on the current pan-cancer analysis, ALYREF may be widespread involved in carcinogenesis in various cancers, including the regulation of cell cycle and apoptosis." (PMID 38491127, 2024). "Notably, we observed that the m6A writer WTAP was located within deletion peaks in 12 cancer types, whereas the m5C reader ALYREF was amplified in 7 cancer types." (PMID 39160604, 2024). "We also identified several ALYREF interaction genes for future cancer research." (PMID 38361753, 2024). "The dysregulation of ALYREF has been reported in a variety of cancers." (PMID 37537569, 2023). "The ALYREF protein acts as a crucial epigenetic regulator in several cancers." (PMID 34367948, 2021). "To explore the pan-cancer gene expression of ALYREF, we used the UALCAN database." (PMID 34367948, 2021). "Collectively, the DNMT3A, DNMT3B, DNMT1, and ALYREF might function as poor prognosis predictors in cancer progression." (PMID 34325709, 2021). "The marked reduction in metastatic capacity and cancer cell proliferation following ALYREF, THOC1 and LUZP4 depletion further suggests that there may be therapeutic benefit in targeting TREX." (PMID 27679854, 2016).